TRAIP (TRAF interacting protein)
Diseases named in the same sentence as TRAIP in open-access papers (continued):
Sharing a sentence is not in itself a finding about the gene and the disease.
tumor (12 papers, 2015 to 2024). "As a master regulator of DNA repair, dysfunction of TRAIP is associated with tumor development and progression." (PMID 36199791, 2022). "The results showed that the protein levels (P < 0.01) of TRAIP in the tumor tissues were markedly higher than those in the corresponding adjacent tissues, suggesting TRAIP was overexpressed in TNBC." (PMID 36064576, 2023). "TRAIP silencing suppressed tumor growth, and rescuing TRAIP expression restored the ability of tumors to grow." (PMID 34349117, 2021). "Increased levels of γH2AX foci were found in the nucleus of the tumours with lower nuclear expression of TRAIP while few γH2AX foci in the patient tissues with higher expression of TRAIP." (PMID 26781088, 2016). "Moreover, the high expression of TRAIP was significantly correlated with tumor recurrence, suggesting that the expression of TRAIP was significantly correlated with the progression of TNBC." (PMID 36064576, 2023). "Moreover, we demonstrated using RNA in situ hybridization the transcriptional induction of TRAIP mRNA in the drug-treated tumors, which was concordant with the protein expression in the matched tumor samples." (PMID 32350249, 2020). "Furthermore, we observed an interesting inverse correlation between nuclear expression of TRAIP and γH2AX foci in these tumours." (PMID 26781088, 2016). "Finally, TRAIP knockdown significantly inhibited tumor growth and metastasis in animal experiments." (PMID 36064576, 2023). "It is possible therefore that the G2 arrest and senescence we observe upon degradation of TRAIP is not compatible with increased proliferation and tumour development." (PMID 37604812, 2023). "As TRAIP acts as an E3 ubiquitin ligase and KANK1 has been identified as a tumor suppressor, we evaluated whether KANK1 was a substrate of TRAIP." (PMID 34349117, 2021). "However, nuclear expression of TRAIP in tumour tissues was markedly reduced compared with each matched normal adjacent tissue." (PMID 26781088, 2016). "The finding that several E2F transcription factors modulate TRAIP expression in a comparable manner is not surprising since these transcription factors may have redundant regulatory roles in normal and tumor cells." (PMID 26369285, 2015).
cancer (10 papers, 2015 to 2023). A tumor composed of atypical neoplastic, often pleomorphic cells that invade other tissues. "TRAIP was a new regulator in DNA damage response and was associated with cancer development in LUAD." (PMID 35884544, 2022). "Moreover, a second pathway of CMG disassembly is activated during mitosis, dependent upon the TRAIP ubiquitin ligase that is mutated in primordial dwarfism and mis‐regulated in various cancers." (PMID 33590678, 2021). "Finally, downregulation or immunodepletion of TRAIP in human cells and Xenopus egg extract system was reported previously to lead to chromosomal instability and re-arrangements, which are a hallmark of cancer development." (PMID 37604812, 2023). "CCK-8 and colony-formation assays were performed to determine the effect of TRAIP depletion on the proliferation in cancer cells." (PMID 36064576, 2023). "In the present study, we found that TRAIP was involved in pathways in cancer, regulation of autophagy, and DNA metabolic process enrichment terms and associated with poor prognosis of LUAD." (PMID 33050659, 2020). "The only intersection was TRAIP, which has been reported as a novel regulator of H2B monoubiquitination in DNA damage response and cancer development in LUAD." (PMID 32121037, 2020). "Nuclear TRAIP expression in 75% cancer tissues was at least twofold lower than that in each corresponding matched normal tissue." (PMID 26781088, 2016). "There exist a positive correlation between EZH2 and the five genes (CHEK1, MAD2L1, RFWD3, TRAIP, and TTK) in the majority of detailed cancer types as shown in the form of heatmap data." (PMID 34381492, 2021). "How TRAIP and CYLD functionally interact in cell cycle regulation and cancer development remains to be explored." (PMID 26369285, 2015). "In addition, patients with recurrence of carcinoma had higher TRAIP expression than those without recurrence (P < 0.05)." (PMID 36064576, 2023).
infection (2 papers, 2018 to 2020). The state of being infected such as from the introduction of a foreign agent such as serum, vaccine, antigenic substance or organism. "PRRSV-induced TRAIP transcription levels peak in early infection, which is consistent with the stage of high transcriptional expression levels of non-structural proteins during PRRSV replication and proliferation." (PMID 30619364, 2018). "As a crucial mechanism of PRRSV, achieving persistent infection and immunosuppression through nsp1α regulation of nuclear/plasma distribution and modification of TRAIP, our results provide a novel target pathway to develop antivirals against PRRSV." (PMID 30619364, 2018). "TRAIP expression was suppressed already in the early phase of infection." (PMID 33013908, 2020).
TRAIP also shares sentences with these, for which no sentence is quoted: Fanconi anaemia (2 papers); DNA repair disorder (1); gastric cancer (1); melanoma (1); metastatic cancer (1); musculoskeletal system diseases (1); Obesity (1); papillary thyroid carcinoma (1); rheumatoid arthritis (1).